KCTD8 (potassium channel tetramerization domain containing 8)
Description:
Auxiliary subunit of GABA-B receptors that determine the pharmacology and kinetics of the receptor response. Increases agonist potency and markedly alter the G protein signaling of the receptors by accelerating onset and promoting desensitization (By similarity).
Tractability: Antibody: UniProt places it where antibodies can reach, with medium confidence; its Gene Ontology location is reachable by antibodies, with medium confidence. PROTAC: ubiquitination databases record sites on it.
Gene: Protein-coding gene on chromosome 4 (44,173,903 to 44,448,928, reverse strand). Ensembl gene ENSG00000183783.
Subcellular location: Presynaptic cell membrane; Postsynaptic cell membrane
Subcellular location (Human Protein Atlas): Cytoplasmic bodies
Gene Ontology:
Molecular function: protein binding; identical protein binding
Biological process: nervous system development; regulation of G protein-coupled receptor signaling pathway; protein homooligomerization
Cellular component: postsynaptic membrane; presynaptic active zone membrane; receptor complex; postsynapse; presynaptic membrane
Genetic constraint (gnomAD): Loss-of-function variants: 24 observed, 28.14 expected, observed/expected ratio (o/e) 0.85, 90% interval 0.62 to 1.2. The upper end of that interval is the gene's LOEUF score, 1.2, which puts it in group 5 of 6, group 1 being the genes least tolerant of losing a copy. Missense variants: 650 observed, 615.94 expected, observed/expected ratio (o/e) 1.06, 90% interval 0.99 to 1.13. Synonymous variants: 290 observed, 264.06 expected, observed/expected ratio (o/e) 1.1, 90% interval 1 to 1.21.
Homologues: Orthologues: chimpanzee KCTD8 (100% identical), macaque KCTD8 (99% identical), pig KCTD8 (99% identical), rabbit KCTD8 (97% identical), mouse Kctd8 (95% identical), rat Kctd8 (94% identical), dog KCTD8 (87% identical), zebrafish kctd8 (66% identical), guinea pig KCTD8 (64% identical), tropical clawed frog KCTD8 (26% identical), Caenorhabditis elegans F32B4.5 (15% identical), Drosophila melanogaster twz (13% identical). Paralogues in human: KCTD16 (56% identical), KCTD12 (38% identical), KCTD18 (17% identical), KCTD19 (17% identical), KCTD15 (15% identical), KCTD1 (15% identical), KCTD14 (14% identical), KCTD21 (14% identical), KCTD7 (13% identical), KCNRG (13% identical), KCTD6 (13% identical), KCTD11 (11% identical), and 1 more.
Diseases named in the same sentence as KCTD8 in open-access papers:
KCTD8 is named in the same sentence as 8 diseases in open-access papers, as found by Europe PMC text mining. Sharing a sentence is not in itself a finding about the gene and the disease. The quoted sentences say what the papers report.
medulloblastoma (2 papers, 2018 to 2019). A malignant, invasive embryonal neoplasm arising from the cerebellum. "Among the 25 human KCTD family members, several have been linked to human cancers, including KCTD8, KCTD12, TNFAIP1 and most notably KCTD11/Ren/KCASH1, a reported tumor suppressor in medulloblastoma, possibly by suppressing Hedgehog signaling." (PMID 30142151, 2018).
breast carcinoma (1 paper, 2021). "Some researchers have reported that hypermethylation of KCTD8 is associated with the occurrence and development of breast cancer, which is consistent with our study." (PMID 34234806, 2021).
esophageal adenocarcinoma (1 paper, 2021). A malignant tumor with glandular differentiation arising predominantly from Barrett mucosa in the lower third of the esophagus. "The combination of SLC26A9 with AP002478.1, BHLHA15, FFAR2, IGFBP1, KCTD8, and PHYHD1 was also identified as a gene signature for personalized prognosis prediction and targeted therapy of esophageal adenocarcinoma." (PMID 35008199, 2021).
cancer (4 papers, 2014 to 2022). A tumor composed of atypical neoplastic, often pleomorphic cells that invade other tissues. "Some genes (e.g. SPINK1 in MAY and ANO4, KCTD8, COL15A1, and KCNH1 in ZMA) are related to cancer and skin properties and may have played a role in adaptation to Mayotte and Madagascar climates by increasing tolerance to thermal stress, humidity, and UV exposition." (PMID 35137043, 2022).
KCTD8 also shares sentences with these, for which no sentence is quoted: schizophrenia (2 papers); tumor (2); brain tumor (1); depression (1).